INS (insulin)
Diseases named in the same sentence as INS in open-access papers (continued):
Sharing a sentence is not in itself a finding about the gene and the disease.
Hypoglycemia (continued). "Individuals that were discharged from the ED following hypoglycemic episodes taking an oral diabetic agent with or without an injectable insulin are at a greater risk of recurrent hypoglycemia leading to a return ED visits within 48 h compared to patients taking insulin alone." (PMID 29799604, 2018). "An important adverse effect associated with insulin-based glycemic control is hypoglycemia." (PMID 29435330, 2018). "Furthermore, a recent systematic review suggests that in insulin-treated T2DM, insulin degludec/insulin aspart 70/30 twice daily is comparable to biphasic insulin aspart 30 twice daily and imposes a lower risk of nocturnal hypoglycemia." (PMID 29508275, 2018). "Rapid acting insulin preparations (Lispro, Aspart and Regular) may cause severe hypoglycemia and should be avoided, with the exception of CSII, while long acting or intermediate acting insulin has been successfully used in these patients." (PMID 28943514, 2018). "Even with low intensity and realtively short duration exercise practiced during the day, an increase in insulin sensitivity can last up to 11–16 h post-exercise which combined with glycogen store replacement can increase the risk of late-onset or nocturnal hypoglycemia." (PMID 30713524, 2018). "In addition, we have recently shown that treatment with a fixed 1:23 ratio of a long-acting glucagon analog and insulin reduced the acute risk of hypoglycemia in streptozotocin (STZ) induced diabetic rats." (PMID 29558502, 2018). "INS RNA expression was only associated with a clinical diagnosis of ‘insulinoma’ (biochemically proven hypoglycemia caused by pNET insulin secretion) in a subset of tumors, and in some tumors there appeared to be INS RNA expression without a documented clinical syndrome." (PMID 30062048, 2018). "In addition, the insulin then bypasses the hepatic metabolism, causing late hypoglycemia due to the prolonged insulin effect." (PMID 30415638, 2018). "Finally, the HARMONY-6 study, which compared albiglutide with insulin lispro in patients treated with insulin glargine, revealed a similar reduction in HbA1c, but with fewer cases of hypoglycemia and greater weight loss." (PMID 28115994, 2017). "The principles of long term management are inhibiting insulin secretion, thereby prevent recurrent hypoglycaemia episodes, provide an age appropriate fasting tolerance and avoid neurological symptoms associated to hypoglycemia." (PMID 28855921, 2017). "Both insulin-induced hypoglycemia and starvation are associated with increased lipolysis." (PMID 28087336, 2017). "However, there remains a varying degree of side effects of insulin therapy including weight gain and risk of hypoglycemia." (PMID 28276512, 2017). "However, reduction of blood glucose with insulin is associated with the risk of severe hypoglycemia." (PMID 28955248, 2017). "Besides, acarbose ranked the best in reducing the risk of neonatal hypoglycemia, followed by metformin (plus insulin when required), insulin, and glyburide." (PMID 28930827, 2017). "It is unknown why the old Chinese patients (≥60 years) tend to have higher incidence of lower nocturnal glucose concentrations, which may be potential risk of nocturnal hypoglycemia, especially after intensive insulin therapy." (PMID 28271075, 2017). "Hyperinsulinaemic hypoglycaemia (HH), the most common cause of severe and persistent hypoglycaemia in neonates and children, is the inappropriate secretion of insulin which occurs despite low plasma glucose levels leading to severe and persistent hypoketotic hypoglycaemia." (PMID 28855921, 2017). "Total bilirubin and serum glucose was also dose dependently reduced, and the observed hypoglycemia may be linked to altered ion channel activity of insulin secreting beta cells as was demonstrated for several NSAIDs." (PMID 29296203, 2017). "Glucagon, in high doses, may cause rebound hypoglycemia due to a paradoxical increase in insulin secretion." (PMID 28855921, 2017).
Hypoglycemia (continued). "Moreover, other oral antidiabetic medications or insulin can be used in combination with sulfonylurea and can substantially increase the risk of hypoglycemia." (PMID 28167928, 2017). "However, the benefits of treatment with insulin are uncertain as insulin infusions substantially increase the risk of hypoglycaemia, both in very preterm infants and in children in intensive care." (PMID 29051825, 2017). "There were three cases (a case of warfarin-associated haematuria, a case of isoniazid-associated liver injury, and a case of insulin-associated hypoglycaemia) where both raters using the WHO-UMC system assessed the case as ‘definite’, while both raters using the LCAT assessed the case as ‘probable’." (PMID 28235001, 2017). "Indeed, a continuous intravenous insulin infusion has been linked to a decreased incidence of hypoglycemia when compared to a bolus injection of insulin." (PMID 28245289, 2017). "In very young children, the GHRH-arginine test may not conclusively differentiate GH deficiency from normal and the insulin tolerance test may result in hypoglycemia due to high sensitivity to insulin." (PMID 29375479, 2017). "Previous studies demonstrated that the use of SAPs with a predictive low-glucose insulin-suspend (PLGS) function could reduce the risk of hypoglycaemia after physical activity." (PMID 28840263, 2017). "Risk of nocturnal hypoglycemia following physical activity may be mitigated with lower basal insulin doses overnight, bedtime snacks, and/or use of CGM, and these strategies should be recommended to assist in preventing delayed-onset lows." (PMID 28265261, 2017). "Moreover, exercise increases insulin sensitivity for up to 72 hours postexercise, which presents a risk of hypoglycaemia during recovery from exercise." (PMID 28634587, 2017). "We aimed to investigate whether day-and-night hybrid closed-loop insulin delivery can improve glucose control while alleviating the risk of hypoglycaemia in adults with HbA1c below 7·5% (58 mmol/mol)." (PMID 28094136, 2017). "Incorrect insulin injection techniques are not only associated with higher consumption of insulin and higher glycated hemoglobin values but also are responsible for higher frequencies of unexpected hypoglycemia and glucose variability." (PMID 29333459, 2017). "In addition, both groups have a large number of subjects under insulin treatment inadequately dosed due to the risk of hypoglycemia especially in the context given by the presence of CKD." (PMID 28392941, 2017). "Improved medication adherence and optimization of these members’ medication regimen to include starting insulin or an oral medication, such as a sulfonylurea, that can cause hypoglycemia could explain this finding." (PMID 28698167, 2017). "In contrast, persisting hypoglycaemia is often caused by a genetic disorder, and may be insulin dependent or insulin independent." (PMID 28566443, 2017). "Furthermore, preserved endogenous insulin secretion prevents potentially harmful iatrogenic hypoglycemia and the increased glucose variability associated with insulin therapy." (PMID 28497374, 2017). "Thus, this was the first study to demonstrate that frequent episodes of hypoglycemia are associated with changes in carotid artery atherosclerosis in insulin-treated patients with T2DM." (PMID 28067320, 2017). "Insulin is considered the most effective and flexible therapy for T2DM but the adverse event profile, especially the risk for severe hypoglycemia and the need for cognition and compliance, make insulin a challenging treatment option for both patients and prescribers." (PMID 27909794, 2017). "Only one study was identified which specifically analysed risks and benefits of combining metformin with other antidiabetic drugs, where risk of hypoglycaemia with the combination of metformin, sulfonylurea and insulin glargine compared to premixed insulin was decreased." (PMID 29047344, 2017).
Hypoglycemia (continued). "While endogenous insulin secretion decreases during or after exercise under normal physiologic conditions, diabetics with a loss of insulin secretory capacity can be put in a severe situation because of hypoglycemia, defined as a blood glucose level below 0.7 mg/mL." (PMID 30400457, 2017). "In the case of missed meals or interrupted nutrition, nurse driven protocols and automated management decision tools for the omission of sulphonylureas and prandial insulin should be implemented locally to reduce the risk of iatrogenic hypoglycemia and standardize care." (PMID 28265893, 2017). "Particularly, strict glycemic control using intensive insulin therapy increases the risk of hypoglycemia and weight gain which might reduce their beneficial effects." (PMID 28250768, 2017). "In patients who have not resumed a normal diet, sulphonylureas such as gliclazide may be withheld because of their insulin secretory effects with potential for causing hypoglycemia." (PMID 28265893, 2017). "Comparisons among insulin analogs that may have greater efficacy or reduced risk for hypoglycemia are limited." (PMID 27188479, 2016). "We hypothesized that the short-acting SQ insulin preparation with the longer duration of action would have a better GV profile, and a smaller risk of hypoglycemia, in the background of continuous enteral feedings when SH is present." (PMID 26819233, 2016). "New generation of basal insulin formulations, with longer length of action, showed the capability of providing adequate glycemic control, in the same extent as insulin glargine, but with decreased risk of hypoglycemia, especially nocturnal episodes." (PMID 26740822, 2016). "The use of insulin was associated with a six times higher risk of hypoglycaemia." (PMID 27380790, 2016). "However, the use of exogenous insulin injections to control blood glucose level puts patients with T1DM at risk of hypoglycemia." (PMID 26807719, 2016). "It is possible that the risk of hypoglycemia could be avoided by dividing the insulin dosage and administering at more frequent intervals." (PMID 27766967, 2016). "Intensive insulin was associated with increased risk of severe hypoglycemia that might explain increased mortality of intensive versus usual insulin." (PMID 26909519, 2016). "However, systematic reviews and meta-analyses of trials comparing basal insulin versus premix concluded that, despite the higher risk of hypoglycemia, glycemic control was greater with premix insulin." (PMID 27760129, 2016). "The secretion of insulin by pancreatic beta cells might be enhanced by atypical antipsychotics and consequently cause hypoglycemia." (PMID 27478670, 2016). "Daily utilization was greatest in patients receiving therapy associated with a pre-defined high risk of hypoglycemia [insulin: basal + bolus (2.16), premixed (1.65), basal (1.16), other insulin regimens (2.13), and sulfonylureas (0.74)] versus non-sulfonylurea non-insulin-based regimens (0.52)." (PMID 26972690, 2016). "Provided the β-cells are fully functional, sulphonylureas such as glibenclamide can cause hypoglycaemia because insulin release is initiated even when glucose concentrations are below the normal threshold for glucose-stimulated insulin release (approximately 5 mmol/L or 90 mg/dL)." (PMID 27208974, 2016). "Additionally, since recently developed technologies including insulin pumps with low glucose suspend software reduce the risk of hypoglycaemia, the restricted goal is safely achievable." (PMID 26881252, 2016). "Furthermore, when compared with a basal-bolus regimen (IDeg OD + IAsp), IDegAsp BID demonstrated comparable glycemic control and risk of overall/nocturnal hypoglycemia with significantly less weight gain and insulin dose requirement." (PMID 27760129, 2016). "Indeed, when empagliflozin was added to insulin in this study, similar levels of glycemic control were achieved with lower doses of insulin and lower risk of hypoglycemia." (PMID 26807719, 2016).
Hypoglycemia (continued). "Furthermore, IDeg in combination with oral antidiabetic drugs provided long-term glycemic control similar to IGlar with a lower risk for nocturnal hypoglycemia in insulin-naïve patients with T2DM." (PMID 27760129, 2016). "Insulin therapy may relieve the burden of proteotoxic insulin in the endoplasmic reticulum, but this of course comes with a well known risk of hypoglycemia that can be fatal." (PMID 28702245, 2016). "This suggests that insulin glargine and NPH insulin may be associated with a lower frequency of symptomatic and severe hypoglycaemia in Chinese paediatric patients with T1DM compared with their European counterparts." (PMID 27887605, 2016). "Diabetic patients on insulin and sulphonylureas are at risk of developing hypoglycaemia." (PMID 27380786, 2016). "Fear of hypoglycaemia may cause overcompensation by ingesting excessive amounts of carbohydrate or reducing insulin doses to a greater degree than necessary, leading to high glucose levels during or after exercise." (PMID 27287376, 2016). "Hypoglycemia was associated with increased mortality risk in the ACCORD trial, and a companion report by Miller and colleagues reported that in patients on any insulin, the risk for hypoglycemia requiring the help of another person increased by more than fourfold." (PMID 27188479, 2016). "Although serum calcium normalized following his neck surgery, he started to present with intermittent symptoms of hypoglycemia such as seizures associated with blood glucose levels of 1.6 to 1.8 mmol/L and serum insulin levels of 18.6 to 27.6 uIU/mL (I/G ratio: 0.63–0.85)." (PMID 27367988, 2016). "Patients on IDegAsp had a significantly higher risk of overall confirmed hypoglycemia compared with those on IGlar that may be associated with the effect of the bolus insulin in IDegAsp and the timing of administration." (PMID 27760129, 2016). "Because the risk of hypoglycemia is increased with using large insulin doses, sufficient glucose (60 grams with the administration of 20 units of insulin and 50 grams with the administration of 10 units) should be given to prevent hypoglycemia, and plasma glucose should be frequently monitored." (PMID 27148740, 2016). "*** Patients undergoing treatment with drugs that cause hypoglycemia (sulfonylureas, metiglinides, or insulin) and have other factors that could increase this risk (depression, lack of social support, lack of appetite, or intolerance to ingestion)." (PMID 27546934, 2016). "Risk of hypoglycaemia is the most important concern in GC implementation; therefore a protocolized approach, comprising a validated insulin administration protocol and use of accurate monitoring technologies is essential for safe GC management in intensive care patients." (PMID 26801983, 2016). "Mixed split insulin regimen was associated with the highest incidence of hypoglycemia." (PMID 27246619, 2016). "Insulin and sulfonylureas are associated with a high risk of hypoglycaemia." (PMID 27356590, 2016). "However, this can result in increased weight gain and hypoglycemia, which is associated with all insulin therapy use but is more pronounced when treatment is intensified with RAI." (PMID 27761472, 2016). "Maybe higher variability within BR causes fluctuations in insulin action potentially contributing to an increased frequency of severe hypoglycemia in this analysis." (PMID 26938444, 2016). "Combination of glucagon inhibition with insulin therapy may however increase the risk of hypoglycemia." (PMID 27092792, 2016). "On the other hand, little has been reported about circulating glucagon levels in such patients, and currently, treatment options consist mainly of full insulin replacement dosing, which of course comes with concomitant risk of unintended – or even fatal – hypoglycemia." (PMID 28702245, 2016).
Hypoglycemia (continued). "However, new generation of basal insulin formulations, with longer length of action, have shown the capability of providing adequate glycemic control with lower risk of hypoglycemia." (PMID 26740822, 2016). "Reducing the insulin dose before a weight loss attempt is important to prevent hypoglycaemia, but it may also enhance weight loss." (PMID 27494531, 2016). "Adjustment of insulin dosage is critical to reduce the risk of hypoglycemia." (PMID 26157708, 2015). "Consequences of hypoglycemia, which in turn can cause injury, myocardial infarction, seizure, stroke or death, are greatest in those who are frail and elderly, with erratic eating habits, on insulin and sulfonylureas, and with CKD." (PMID 28702221, 2015). "If preprandial short-acting insulin could be removed her risk of hypoglycemia which had been a problem (three or four events per week) would be much less." (PMID 25785209, 2015). "Insulin often causes significant hypoglycaemia in addition to weight gain, and clinical trials such as ACCORD, ADVANCE, and VADT have suggested that mortality rates may be increased in patients with episodes of severe hypoglycaemia." (PMID 25645672, 2015). "Symptomatic hypoglycemia, resulting in brain dysfunction ranging from mild behavioral impairments to coma, is the principal problem associated with tight glucose regulation in patients undergoing insulin therapy." (PMID 26553727, 2015). "The risk of hypoglycemia is high in adjunctive therapy of Pramlintide with insulin." (PMID 26157708, 2015). "The increased incidence of hypoglycemia in patients with increased weight loss might also signal a greater responsiveness (e.g., more insulin secretion) to exenatide therapy." (PMID 25645567, 2015). "This makes GLP-1 an attractive therapeutic target, because it enhances insulin secretion only in response to a meal, when it is needed, and not during inter-meal intervals when it could increase the risk of hypoglycemia." (PMID 25982967, 2015). "A potential clinical question linked to SGLT2 inhibitor therapy as adjunctive-to-insulin in T1DM is the degree of possible insulin dose adjustment that may be required upon initiation of treatment to minimize a potential hypoglycemia risk." (PMID 26544192, 2015). "However, several trials have reported that strict glucose control with insulin in patients with TBI is associated with variable degrees of hypoglycemia." (PMID 25822252, 2015). "As a result, IAb-associated hypoglycemia should be considered when initiating insulin therapy." (PMID 25961056, 2015). "Simple increase of insulin potency alone is similar to dose elevation and could lead to a higher incidence of hypoglycemia, which is the major risk factor of marketed insulin and insulin analogs." (PMID 25799496, 2015). "Indeed, a reduction of the pre-meal insulin dose is often suggested to minimize the risk of exercise-induced hypoglycemia." (PMID 25918842, 2015). "In the present study, we tended to retrospectively analyze the clinical characteristics of a cohort of patients with hypoglycemia associated with IAbs induced by exogenous insulin in a tertiary referral center, to help clinicians better understand the manifestation and management of such condition." (PMID 25961056, 2015). "This is principally related to the risk of hypoglycemia associated with insulin therapy." (PMID 28702227, 2015). "Using an insulin pump may cause a more predictable blood glucose concentration and less need for preventive behavior to avoid hypoglycemia than using insulin injections does." (PMID 25599725, 2015). "Although some drug treatments such as use of insulin and secretagogues are associated with higher rates of hypoglycaemia, occurrence of hypoglycaemia itself may contribute to increased risk of CVD as well as multidimensional impairment in T2D." (PMID 26504840, 2015).